HDAC6 (histone deacetylase 6)
Diseases named in the same sentence as HDAC6 in open-access papers (continued):
Sharing a sentence is not in itself a finding about the gene and the disease.
ovarian carcinoma (continued). "For example, the synergistic effects of HDAC6 inhibition and bortezomib induced apoptotic cell death in ovarian cancer cells, whereas HDAC6 knockdown markedly reduced the migration and invasion activity of hepatocellular carcinoma cells." (PMID 30594243, 2018). "Increased HDAC6 levels have been noted in certain tumor types, such as oral squamous cell cancer, ovarian cancer and glioma." (PMID 24795145, 2014). "HDAC6 does influence the pathways of ovarian cancer through its effects on the stress response, oncogenesis, cell motility, and many other cancer-related signaling networks." (PMID 23644884, 2013). "The idea of using HDAC6 as a target for cancer treatment continues to expand in recent years, and more potent and specific HDAC6 inhibitors are required to effectively down-regulate the tumor-prone cell signaling pathways responsible for ovarian cancer." (PMID 23644884, 2013). "This combination therapy of inhibiting both the proteasome and HDAC6 also seemed to work well in ovarian cancer cells with the treatment of bortezomib and the HDAC6-specific inhibitor NK84." (PMID 23644884, 2013). "In their study, tumor growth of HDAC6 knockdown ovarian cancer cells was significantly retarded as compared with that of control cancer cells." (PMID 22957056, 2012). "We evaluated the acetylation status in A2780 ovarian carcinoma cells of H3, which is acetylated through class I HDACs, and tubulin, which is acetylated by the class II family member HDAC6." (PMID 18000499, 2007). "This study has provided evidence to support that the combination of selective HDAC6 inhibitors and Taxol may be a promising treatment strategy for ovarian cancer and encourages further investigation." (PMID 40649308, 2025). "In W1 ovarian cancer cells, our lead structurefor dual Sirt2/HDAC6 inhibition evoked enhanced effects on cell viabilitycompared to single or combination treatment with the unconjugatedSirt2 and HDAC6 inhibitors." (PMID 37902787, 2023). "HDAC6 can promote ovarian cancer cell motility by deacetylating tubulin." (PMID 37894746, 2023). "HDAC6 is overexpressed in ovarian cancer and is known to be correlated with tumorigenesis." (PMID 35955780, 2022). "Compound H42 inhibited ovarian cancer cell proliferation via HDAC6-mediated cyclin D1 degradation and suppressed ovarian cancer progression in nude xenograft mice, indicating compound H42 has a preclinical value in ovarian cancer therapeutics, warranting further investigation." (PMID 36467091, 2022). "To determine whether HDAC6 inhibition is a viable therapeutic strategy for ovarian cancer, we measured the protein levels of HDACs 1, 2, and 6 in human ovarian cancer cell lines." (PMID 32103105, 2020). "The objective of this study was, firstly, to investigate the relationship between Histone deacetylase 6 (HDAC6) expression and survival in patients with ovarian cancer and, secondly, to test the effects of histone deacetylase 6 (HDAC6) inhibition on ovarian cancer cells in vitro." (PMID 33322608, 2020). "Overexpression of both USP10 and HDAC6 has been observed in lung and ovarian cancer." (PMID 32382008, 2020). "Resistance to paclitaxel, a first line therapy in the treatment for ovarian cancer, was reversed with HDAC6 inhibition in which combination treatment of HDAC6i and Paclitaxel resulted in the synergistic killing of resistant ovarian cancer cells in vitro and in vivo." (PMID 33322608, 2020). "Just last year, tubastatin A, an HDAC6-selective inhibitor, showed strong anti-ovarian cancer tendencies, and the same thailandepsins along with romidepsin showed promising inhibition of ovarian cancer DNA damage response pathways." (PMID 23644884, 2013). "Recently, we found that HDAC6 protein levels are elevated in a panel of ovarian cancer tissue samples compared with the benign samples (our unpublished data), suggesting that HDAC6 may play a critical role in ovarian cancer development." (PMID 23644884, 2013).
ovarian carcinoma (continued). "All HDAC inhibitors examined in this study (R306465, vorinostat, panobinostat and TSA) showed comparable potency towards both catalytic domains of cellular HDAC6, since tubulin acetylation and inhibition of Hsp90 function were observed at similar concentrations in A2780 ovarian carcinoma cells." (PMID 18000499, 2007). "Therefore, targeting HDAC6 presents a promising therapeutic approach against ovarian cancer." (PMID 40649308, 2025). "However, the overexpression of HDAC6 in HGSOC cell lines is associated with higher migration and proliferation rates in which low HDAC6 expression in ovarian cancer cells may represent a hard-to-treat tumour phenotype associated with increased senescence." (PMID 39941046, 2025). "In addition, targeting the ubiquitin-proteasome system (UPS), with Bortezomib, combined with HDAC6 inhibition was shown to (i) successfully kill ovarian cancer cells in vitro and (ii) reduce ovarian cancer cell spreading and migration as a result of the deacetylation of α-tubulin by HDAC6." (PMID 33322608, 2020). "Silencing of HDAC1 in ovarian cancer cells was found to overcome resistance to cisplatin, and silencing of both HDAC1 and HDAC6 was found to enhance cytarabine-induced apoptosis of acute myeloid leukemia (AML) cells induced by cytarabine." (PMID 38004560, 2023). "Various studies have analyzed the anti-cancer effect of the HDAC6 inhibitor, ACY-241, and its combination effect with standard platinum/taxane chemotherapy in different types of cancer, including ovarian cancer." (PMID 35955780, 2022). "In Caco-2 (colorectal cancer) and OVCAR-8 (ovarian cancer) cells, CD133 binds Histone Deacetylase 6 (HDAC6) and CD133 is degraded by lysosomes." (PMID 35111082, 2021). "In summary, we demonstrated, for the first time, that HDAC6 over-expression in HGSOC and all ovarian cancers is a favorable prognostic marker." (PMID 33322608, 2020). "Therefore, we present the first study to demonstrate that low HDAC6 expression is significantly associated with poorer overall survival by a univariate and multivariate analysis of IHC in HGSOC specimens, as well as a meta-analysis of mRNA expression in ovarian cancer." (PMID 33322608, 2020). "In an attempt to establish the correlation between USP10 and HDAC6 expression in cancer cell lines, we examined USP10 and HDAC6 protein levels in eight lung cancer lines and nine ovarian cancer cell lines." (PMID 32382008, 2020). "When using HDAC isotype-specific substrates, R306465 showed poor inhibition of deacetylation of an HDAC6-specific synthetic substrate, which was confirmed while analysing HDAC1–3 (H3) and HDAC6 substrates (Tubulin, Hsp90) in A2780 ovarian carcinoma cells." (PMID 18000499, 2007). "Furthermore, it has been reported that HDAC6 inhibitors such as ACY-241 (citarinostat) and A452 enhance the activity of paclitaxel in ovarian cancer cells." (PMID 40649308, 2025). "We screened 46 potential novel HDAC6 inhibitors in ES-2 ovarian cancer cells and showed that compound 25253 demonstrated the most potent anti-proliferative activity and effective synergy with paclitaxel, which was also validated in TOV21G ovarian cancer cells." (PMID 40649308, 2025). "Further investigation is required to determine whether inhibition of HDAC6 and HDAC8 has synergistic anti-cancer effects in solid tumors beyond ovarian cancer." (PMID 35955780, 2022). "In A2780 ovarian cancer cells, 24 hour treatment with 300 nM ACY-241 resulted in increased hyperacetylation of α-tubulin, consistent with inhibition of the tubulin deacetylase HDAC6." (PMID 27926524, 2017). "In the same year, bortezomib and an HDAC6 inhibitor, NK84, were found to kill ovarian cancer cells." (PMID 23644884, 2013).
ovarian carcinoma (continued). "Decreased cell viability with this HDAC6 targeting PROTAC was previously shown to result from targeted degradation of IKAROS family zinc finger (IKZF) proteins at micromolar doses, although we did not measure any significant expression of IKZF1 and IKZF2 in ovarian cancers." (PMID 33322608, 2020). "Although HDAC6 becomes over-expressed in cancer, there are too few studies to directly evaluate this in ovarian cancer and no reported studies profiling HDAC6 expression comparing the expression in normal fallopian tubes with HGSOC precancerous lesions and to HGSOC." (PMID 33322608, 2020).
glioma (42 papers, 2014 to 2026). A benign or malignant brain and spinal cord tumor that arises from glial cells (astrocytes, oligodendrocytes, ependymal cells). "We have found that inhibitors of HDAC6 cause rapid and specific changes inside glioma cilia, reducing tumor cell proliferative capacity and promoting cell differentiation." (PMID 33915983, 2021). "Indeed, HDAC6 has been associated with glioma stem cell survival, and inhibition of HDAC6 has been linked to GSC differentiation and increased sensitivity to chemotherapy." (PMID 41471109, 2025). "Consequently, we studied the levels of HDAC1 and HDAC6 in glioma samples of different grades and associated their expression to patient survival." (PMID 32488056, 2020). "Moreover, knockdown and overexpression experiments have shown that HDAC6 controls hallmark features of glioblastoma, which include proliferation, invasion and migration, as well as angiogenesis and apoptosis, and the maintenance of the glioma stem cell population." (PMID 41471109, 2025). "HDAC-MB, a novel multifunctional small-molecule probe designed for glioma theranostics, combines HDAC6 imaging, MAO A inhibition, and photodynamic therapy functions." (PMID 40565099, 2025). "In this context, HDAC6 pharmacological inhibition has been shown to decrease cell proliferation and migration in glioma cells, reduce the activity of glioma stem cells and reduce the growth of both TMZ-sensitive and TMZ-resistant cells in vivo." (PMID 41471109, 2025). "Both compounds increased the levels of acetyl-α-tubulin in both glioma cell types in a dose-dependent manner, confirming HDAC6 inhibition." (PMID 41471109, 2025). "Our analysis showed a change in FASN mRNA expression only with HDAC6 knockdown in IDH1 MT glioma cell line HK252." (PMID 39149696, 2024). "It has also been reported that HDAC6 inhibition enhances the radiosensitivity of cancer cells in lung cancer, glioma, and bladder cancer." (PMID 39063958, 2024). "HDAC6 promotes glioma cell proliferation and confers TMZ resistance to glioma cells, mainly by stabilizing and activating EGFR." (PMID 39057168, 2024). "We further find that HDACs are involved in the regulation of lipogenic genes and HDAC6 is particularly important for the regulation of FASN in IDH1 MT glioma." (PMID 39149696, 2024). "Of note, HDAC6 signaling at primary cilia was previously shown to promote proliferation and to restrict differentiation of glioma cells." (PMID 38655699, 2024). "26,27 Other notable transcriptional differences in EGFRvIII-containing samples include increased HDAC6 expression, reported to promote glioma proliferation; increased expression of the stem cell marker SOX9; and increased expression of tumor suppressor TSC2." (PMID 38665799, 2024). "There are a few HDAC6 clinical candidates for the treatment of mostly non-CNS cancers as their pharmacokinetic liabilities exclude them from targeting HDAC6-implicated neurological diseases, urging development to address these challenges." (PMID 39598445, 2024). "For example, histone deacetylase 6 (HDAC6) inhibition can trigger glioma stem cell differentiation by suppressing SHH signaling." (PMID 37830570, 2023). "HDAC6 has been shown to promote the proliferation of glioma cells through the primary cilia, MKK7/JNK/c-Jun signaling pathway and attenuating transforming growth factor β (TGFβ) receptor signaling." (PMID 37259375, 2023). "For example, selective inhibition of HDAC6 with TubA reverses the malignant phenotype of GBM cells by increasing TMZ-induced apoptosis while the blockade of Hh signal prevents glioma stem cell (GSCs) survival." (PMID 36982845, 2023). "Previous works have demonstrated that the combined inhibition of HDAC6 and Hh pathway using TubA and cyclo treatment effectively reduces glioma cells’ clonogenicity and migration capacity." (PMID 36982845, 2023). "HDAC6 was also enriched in glioma stem cells,and its expression positively correlated with several GSC markers(SOX2, SOX9, CD133, NESTIN, and OCT4)." (PMID 35786935, 2022).
glioma (continued). "For instance, HDAC4 and HDAC6 have been indicated to make glioma cells resistant to radiation by maintaining DNA double-strand damage repair and stemness." (PMID 35193602, 2022). "Univariate Cox regression indicated that high expression levels of HDAC1, HDAC3, HDAC7 and HDAC9 were associated with poor OS of glioma, and elevated expression levels of HDAC4, HDAC5, HDAC6 and HDAC11 were associated with a favorable prognosis of glioma." (PMID 35545840, 2022). "Lastly, we wanted to examine the relationship between cilia frequency in glioma and HDAC6 expression levels." (PMID 33915983, 2021). "HDAC6 inhibitors can significantly reduce glioma cell proliferation by disrupting the G2/M transition, increasing cell death, and promoting cell cycle exit and tumor cell differentiation." (PMID 33915983, 2021). "Together, these data suggest that cilia play a crucial role in HDAC6 functions in glioma cell proliferation and that inhibiting HDAC6′s cilia-mediated function promotes the differentiation of tumor cells." (PMID 33915983, 2021). "Together, our results are consistent with recent findings and show that inhibitors of HDAC6 prevent the proliferation of glioma cells by promoting cell death and cell cycle arrest." (PMID 33915983, 2021). "Our study links these two major phenomena in glioma and suggests that the cilium is essential for HDAC6 functions in maintaining the tumor’s proliferative state." (PMID 33915983, 2021). "We find that blocking HDAC6 function reduces ciliated glioma cell proliferation and promotes their differentiation." (PMID 33915983, 2021). "Our data suggest that HDAC6 interactions with glioma cilia are essential for these tumors to maintain a proliferative state." (PMID 33915983, 2021). "Previous studies in non-glioma cells have found that the effects of HDAC6 inhibitors on cell proliferation are cilia dependent." (PMID 33915983, 2021). "We next examined if the antiproliferative effects of HDAC6 inhibitors are influenced by the presence of glioma cilia." (PMID 33915983, 2021). "HDAC6 inhibitors have been reported to reverse the malignant phenotype of glioma cells by forcing their differentiation, as measured by reduction of the proliferative marker Ki67 and enhancement of differentiation markers such as TUJ1." (PMID 33915983, 2021). "Our findings reveal a conserved and critical role for HDAC6 in glioma growth that is dependent on cilia." (PMID 33915983, 2021). "We show that inhibiting HDAC6 activity increases the number of ciliated glioma cells while reducing the level of acetylated alpha-tubulin in primary cilia." (PMID 33915983, 2021). "Collectively, our findings suggest that HDAC6 promotes the proliferation of glioma cells through primary cilia." (PMID 33915983, 2021). "It revealed that HDAC1 and HDAC6 were significantly over-expressed and within the top 5% gene rank in glioma compared to the normal group, which was evidenced by three and two studies, respectively." (PMID 34540896, 2021). "Altogether, these findings show that HDAC6 inhibitors induce a rapid but differential subcellular response in the degree of acetylation of alpha-tubulin in ciliated glioma cells." (PMID 33915983, 2021). "MPT0B291 is relatively selective in HDAC6 inhibition in glioma cells within 10 min (suggested by manufacturer of HDAC6 activity assay kit)." (PMID 33162824, 2020). "Herein, we extend this analysis to several cohorts, comprising data of over 500 samples, and determine that GBM samples present overexpression of HDAC6 and that its high expression correlates with advanced glioma grade and poor patient survival." (PMID 32488056, 2020).